TRIB3 (tribbles pseudokinase 3)
Diseases named in the same sentence as TRIB3 in open-access papers (continued):
Sharing a sentence is not in itself a finding about the gene and the disease.
lung carcinoma (29 papers, 2016 to 2025). "In our study, we demonstrated the aberrant upregulation of TRIB3 correlated with the lung cancer progression, which was associated with the SOX2 transcription factor activation." (PMID 35473511, 2022). "Our further analysis revealed that TRIB3 was significantly upregulated in lung tumor tissues and correlated with the poor outcome in clinical patients, indicating the potential role of TRIB3 in diagnostic and prognostic estimation for patients with lung cancer." (PMID 35473511, 2022). "In response to ginsenoside Rh2, a bioactive compound in ginseng, lung cancer cells upregulated c-Myc, leading to the accumulation of so-called aggresomes containing tribbles homolog 3 (TRIB3) and p62, thereby triggering paraptosis." (PMID 39519031, 2024). "In conclusion, our study suggested that TRIB3 links integrin αvβ3 signals to induce lung cancer progression, which was coordinated with AKT/SOX2 signals." (PMID 35473511, 2022). "In lung cancer cells, TRIB3 has been found to regulate cell apoptosis by activating nuclear factor-κB signaling." (PMID 35152840, 2022). "In mechanism, the interaction between AKT and TRIB3 was necessary for the FOXO1/AKT/SOX2 activation in lung cancer." (PMID 35473511, 2022). "Intervention of PIERCE and AKT in ER stress-induced TRIB3 expression shows that PIERCE1 modulates AKT phosphorylation in mutant KRAS-driven lung cancer." (PMID 32728173, 2020). "Many kinds of research indicate that TRIB3 promotes the emergence and gradual growth of various types of cancers, such as gastric cancer, renal cancer, lung cancer, oral cancer, and is closely related to poor prognosis." (PMID 32160655, 2020). "It has been reported that TRIB3 regulated Notch1 activation in lung cancer cells and Notch1 activation is known to lead to radioresistance of TNBCs." (PMID 30678233, 2019). "Our study suggested that integrin αvβ3 could efficiently promote lung cancer cell proliferation and stem-like phenotypes in a tribbles homolog 3 (TRIB3) dependent manner." (PMID 35473511, 2022). "Given the crucial role of TRIB3 in a variety of pro-tumor signals, we wondered whether TRIB3 contributed to the pathogenesis of lung cancer and correlated with the prognosis of patients." (PMID 35473511, 2022). "Similarly, in aggressive lung cancer cell lines, TRIB3 depletion is correlated with Notch1 downregulation and inhibition of tumor growth and metastatic dissemination." (PMID 33920424, 2021). "Zhou et al25 reported that knocked out TRIB3 in invasive lung cancer cell lines could inhibit malignant behavior in vitro significantly, such as cell invasion and proliferation, and inhibit the metastasis and growth of tumors in vivo." (PMID 32160655, 2020). "Furthermore, quantitative analysis of PIERCE1 and TRIB3 expression in lung cancer patients revealed their negative interrelationship, thereby confirming the correlation that PIERCE1 suppresses TRIB3 in human lung cancer patients." (PMID 32728173, 2020). "The stable expression of uc002wdm/NM_021158 (TRIB3) was detected in most cases of lung cancer." (PMID 28105922, 2016). "Interestingly, it was recently shown that increased levels of TRIB3 were associated with elevated EGFR stability and signaling activity in lung cancer, suggesting that the disruption of the TRIB3-EGFR interaction could be a novel therapeutic target." (PMID 34198908, 2021). "Here, we reported in the present study that integrin αvβ3 facilitated the lung cancer proliferation and invasion through FAK/AKT signaling pathway, which was dependent on the collaboration with TRIB3." (PMID 35473511, 2022). "Interrupt of TRIB3/AKT axis by Pep2–Ae efficiently improved the outcome of chemotherapy, which describing an innovative approach for lung cancer treatment." (PMID 35473511, 2022). "Meanwhile, activated TRIB3 interacted with AKT to upregulated FOXO1 and SOX2 expression, resulting in sustained tumor progression in lung cancer." (PMID 35473511, 2022).
lung carcinoma (continued). "Interrupting the interaction between TRIB3 and AKT contributed to suppression of lung cancer progression induced by integrin αvβ3." (PMID 35473511, 2022). "Because several genes, including DDIT3, TRIB3, and ATF3, were specifically increased due to verteporfin treatment in KRAS-mutant lung cancer cells, we focused on the ER stress pathway." (PMID 33830081, 2021). "To determine the relationship between TRIB3 and EGFR levels in lung cancer, we detected the expression of these two proteins in several human lung cancer cell lines." (PMID 32694521, 2020). "As a result, the colorectal, liver, and lung cancer exhibit higher TRIB3 mRNA level as compared with non-tumor sample." (PMID 33920424, 2021). "Studies have demonstrated that the interaction between tribbles homolog 3 (TRIB3) and β-catenin increases the recruitment of β-catenin to the promoter region of Wnt regulatory genes, thereby promoting the migration, invasion, and EMT of lung cancer cells." (PMID 33988228, 2021). "In addition, insulin and IGF-1 induced TRIB3 protein expression in human colon cancer HCT-8 cells, as well as in hepatoma HepG2 and lung cancer A549 cell lines." (PMID 34198908, 2021). "Consistently with previous results herein described for colon, but not concerning liver, an additional report showed high levels of TRIB3 in both colon cancer, hepatocellular carcinoma (HCC), and lung cancer tumor tissues, when compared with adjacent non-tumor tissues." (PMID 34198908, 2021).
diabetes (20 papers, 2011 to 2025). "For example, altered TRIB3 expression has been associated with diabetes, hepatitis, neurodegenerative disorders, and tissue fibrosis." (PMID 38733632, 2024). "Many studies have shown that TRIB3 gene variation or its altered expression plays an important role in the risk and progression of diabetes and vascular complications." (PMID 36105108, 2022). "Some low-frequency genetic variants detected by re-sequencing of TRIB3 can partially account for cardiovascular clinical outcomes in diabetes." (PMID 30971918, 2019). "Research suggests that TRIB3 interacts with different regulatory genes to govern several diseases, including diabetes, hepatitis, and tissue fibrosis." (PMID 40157922, 2025). "A model of CKD combined with diabetes and hyperlipidemia was developed to investigate the role of TRIB3 in metabolic CKD." (PMID 39932798, 2025). "Recently, TRIB3 has been proven to be an ER stress and metabolic sensor involved in glucose and lipid metabolism and contributes to diabetes and related cardiovascular diseases." (PMID 39932798, 2025). "Other genes encode proteins involved in calcium handling (BMP3 and SYNDIG1) or are associated with diabetes mellitus (GLIS3 and TRIB3), suggesting a potential link to accelerated atherosclerosis development." (PMID 38725839, 2024). "TRIB3, a stress sensor, is involved in the pathogenesis of various diseases, including obesity, diabetes, and tumors." (PMID 35668944, 2022). "A recent paper in Nature Communications shows that pseudokinase TRIB3 has a critical role in the development of diabetes‐related cancers via interacting with SQSTM1, a selective autophagy receptor." (PMID 27038142, 2016). "Oxidative stress enhances C/EBP homologous protein (CHOP), a marker of endoplasmic reticulum (ER) stress, and increases the binding of CHOP to the Trib3 promoter in murine diabetic kidneys." (PMID 27977799, 2016). "Hepatic Trib3 expression is reported to be highly expressed in animal models of diabetes, hence promoting hyperglycemia presumably by increasing glucose production in the liver." (PMID 26441828, 2015). "Nonetheless, whether the shift of TRIB3 transcriptional activity has the effect of inducing diabetic vascular complications is still unclear." (PMID 36105108, 2022). "Furthermore, the documented role of TRIB3 as a nexus between diabetes and cancer can inform tests of Trbl in recently developed fly insulin-regulated tumor models." (PMID 29025897, 2017). "In addition, sitagliptin treatment totally (p < 0.001) prevented the diabetes-induced increment (p < 0.001) in TRIB3 expression in the pancreatic tissue." (PMID 24650557, 2014). "Furthermore, TRIB3 has a role in insulin sensitivity and diabetes and has also been described to interact as a scaffold protein in multiple signaling cascades, including v-akt murine thymoma viral oncogene homolog 1 (PKB/Akt) but also MAPK pathways." (PMID 21864376, 2011). "So, TRIB3 may be used as a therapeutic target or indicator for diabetes and its complications." (PMID 36105108, 2022). "In the current article, GEO database analysis showed that in contrast to normal podocytes, TRIB3 expression was remarkably higher in HG-induced podocytes and renal cortical tissues from STZ-induced diabetes." (PMID 38733632, 2024). "Our recently published study has demonstrated that CRC patients with diabetes exhibit higher expression of p300 and TRIB3 than that of nondiabetic patients." (PMID 36577755, 2022). "Additionally, overexpression of tribbles homolog 3 (TRIB3) protein, a regulator of insulin signaling in diabetes, can reduce Müller cell viability." (PMID 36016568, 2022).
glioma (16 papers, 2010 to 2025). A benign or malignant brain and spinal cord tumor that arises from glial cells (astrocytes, oligodendrocytes, ependymal cells). "The binding of THC to receptors in glioma causes accumulation of ceramide which puts stress on the ER and leads to pseudokinase tribbles homologue-3 (TRIB3)-dependent inhibition of AKT/mTOR." (PMID 33802014, 2021). "Further, cannabinoid-mediated apoptosis is associated with the upregulation of ATF4, DDIT3, and TRIB3 in cannabinoid-sensitive glioma cells." (PMID 29290987, 2017). "In fact, this is logical in the context of our analysis, as the hypoxia-upregulated U87-MG-specific miR-26b-5p (as it was mentioned a “general suppressor”) can potentially inhibit TRIB3 activity (“glioma oncogene”) in a ceRNA manner." (PMID 39457549, 2024). "Further evidence of the stimulation of p8/TRIB3 pathway was observed in glioma patients treated with THC." (PMID 33802014, 2021). "To explore the function of TRIB3 in glioma, we transfected glioma cell lines with lentivirus carrying TRIB3 or vector, and the overexpression efficiency was verified by Western blot (data not shown)." (PMID 33203798, 2020). "In this study, we demonstrate TRIB3 as a tumor promoter in glioma by combining in vitro and in vivo analyses." (PMID 33203798, 2020). "We began with analyzing the expression of TRIB3 in the Cancer Genome Atlas (TCGA) and found that the expression of TRIB3 in gliomas was increased compared with that in normal brain tissues (NBTs)." (PMID 33203798, 2020). "We predict that TRIB3 is a potential novel therapeutic target for the treatment of glioma that can be applied in the future." (PMID 33203798, 2020). "To further explore the function of TRIB3 in glioma, we transfected glioma cell lines with a plasmid carrying shRNA targeting TRIB3 (sh-TRIB3-1 and sh-TRIB3-2), and the knockdown efficiency was verified by Western blot analysis (data not shown)." (PMID 33203798, 2020). "HE staining of the lungs of the different groups also showed that sh-TRIB3 inhibited the occupation of glioma in the lungs." (PMID 33203798, 2020). "Next, we detected the expression of TRIB3 in glioma cell lines (U251, A172, LN229, U87, T98G, and U87MG) and the normal human cell line HMG3, HAs, primary microglial cells and primary astrocytes." (PMID 33203798, 2020). "TRIB3 is also expected to be a new target for glioma treatment." (PMID 39118481, 2024). "We examined several biomarkers that are not routinely used in glioma IHC detection and found that TRIB3 and AURKA were associated with poor prognosis of the disease." (PMID 39118481, 2024). "Our study revealed that TRIB3 plays an important role in the promotion of glioma development and progression by suppressing autophagic flux, which drives the invasion and proliferation of GBM cells, suggesting that TRIB3 is a potential novel therapeutic target for the treatment of glioma." (PMID 33203798, 2020). "Compared with that in NBTs, the mRNA level of TRIB3 was higher in glioma tissue." (PMID 33203798, 2020). "To explore the effect of TRIB3 inhibition on glioma growth, we used a xenograft mouse model." (PMID 33203798, 2020). "TRIB3 was upregulated in glioma cell lines, especially in U87 and U251 cells." (PMID 33203798, 2020). "Our study revealed that TRIB3 plays a critical role in the promotion of glioma development and progression, but these protective effects were abolished by the autophagic flux inhibitor CQ in vivo and in vitro, indicating that autophagic flux inhibits the invasion and proliferation of GBM cells." (PMID 33203798, 2020). "Whether TRIB3 regulates the progression of glioma by modulating autophagy is still unknown." (PMID 33203798, 2020). "Increased levels of TRIB3 inhibited AKT activity and consequently induced cell death via FOXO in glioma cells." (PMID 34198908, 2021).
glioma (continued). "In agreement, THC induced an ER-stress response in human and mouse glioma cells that promoted autophagy and apoptosis via TRIB3, inducing expression of ATF4, CHOP, and TRIB3 genes." (PMID 33916466, 2021). "We also divided the glioma tissue into three different grades according to the histopathological classifications formulated by WHO and found that the mRNA level of TRIB3 was related to the grade of glioma." (PMID 33203798, 2020). "It is anticipated that further investigation into TRIB3 and AURKA could lead to the development of novel therapeutic targets for glioma, such as MGMT and EGFR." (PMID 39118481, 2024). "In addition, we also detected the expression of Trib2 and Trib3 in the glioma cells, which was not altered by irradiation (data not shown)." (PMID 26521947, 2015).
melanoma (14 papers, 2007 to 2024). A malignant, usually aggressive tumor composed of atypical, neoplastic melanocytes. "Other studies have demonstrated that inhibition of TRIB3 expression by metformin can induce autophagy, thereby preventing melanoma progression." (PMID 39044829, 2024). "For example, via suppressing autophagy and ubiquitin–proteasome degradation processes, TRIB3 can promote melanoma progression." (PMID 37268878, 2023). "To validate the results at the protein level, we performed immunohistochemistry of TRIB3 and SLC12A9 (risk genes) in metastatic and primary melanoma tissues." (PMID 37268878, 2023). "By activating autophagic flux and the ubiquitin-proteasome system, inhibiting TRIB3 or interrupting the TRIB3-SQSTM1 interaction can attenuate melanoma growth and metastasis." (PMID 33203798, 2020). "Further studies are therefore invited to explore the putative therapeutic potential of modulating TRIB3 expression/activity in melanoma." (PMID 30845666, 2019). "In another study, metformin induced autophagy activation in melanoma cells by inhibiting a new potential therapeutic target, tribbles pseudokinase 3 (TRIB3)." (PMID 30186236, 2018). "In humans, Trib2 has been identified as a repressor of FoxO in malignant melanomas and complimentarily, FoxO represses Trib3 expression to derepress Akt and enhance insulin sensitivity in hepatocytes." (PMID 25329475, 2014). "Other investigators also demonstrated that metformin could restore autophagic flux in melanoma cells and saturated fatty acid-challenged endothelial cells via a TRIB3- and AMPK-dependent mechanism, respectively." (PMID 34997207, 2022). "Moreover, suppression of TRIB3 was found to restore autophagy flux; thus, these data suggested that down-regulating expression and/or inhibiting activity of TRIB3 may be a potent anti-melanoma strategy." (PMID 30845666, 2019). "For instance, metformin arrests melanoma cells in the G0/G1 phase and attenuates melanoma growth and metastasis by inhibiting the expression of TRB3 (tribbles pseudokinase 3) in vivo." (PMID 37370809, 2023). "The gene-signature contained three genes, including TRIB3, TMEM101, and SLC12A9, of which some have been reported to be correlated to melanoma and other tumors." (PMID 37268878, 2023). "In this study, the authors showed that metformin attenuated melanoma growth and metastasis by reducing TRIB3 expression in non-diabetic and diabetic mouse models." (PMID 30186236, 2018).
Obesity (13 papers, 2017 to 2025). Accumulation of substantial excess body fat. "Mice deficient in Trib3 are resistant to diet-induced obesity and exhibit improved glucose homeostasis due to enhanced BAT activity." (PMID 39623091, 2024). "Here, using Trib3 KO mice, the associations between Trib3 and overnutrition, aging-related obesity, and its role in energy expenditure in brown adipocytes are investigated." (PMID 39623091, 2024). "We speculated that the increase in Trib3 expression under conditions of diet-induced obesity could be associated with FFAs, the DAG‒PKC signaling axis, or both." (PMID 39623091, 2024). "These indicate that TRIB3 might inhibit subcutaneous fat deposition in LY pig and be closely related to obesity-associated diseases." (PMID 29152100, 2017). "Researchers discovered that Trib3 knockout mice, which lack the Trib3 gene, are resistant to diet and aging-induced obesity." (PMID 39623091, 2024). "Trib3 KO mice are resistant to diet-induced obesity, resulting in reduced adiposity and body weight and better maintenance of glucose homeostasis." (PMID 39623091, 2024). "Accordingly, Trib3 expression is elevated in major metabolism-related tissues of humans and rodents under fasting conditions and nutrient-excess conditions such as obesity or diabetes." (PMID 39623091, 2024). "Researchers conducted experiments on Trib3 KO mice to examine their resistance to obesity using methods like glucose tolerance tests, indirect calorimetry, and PET imaging to analyze the mice." (PMID 39623091, 2024). "TRIB3 was reported to be upregulated in the adipose tissue of obesity subjects; meanwhile, another report declared that TRIB3 promoted the cholesterol accumulation in the macrophage." (PMID 35499169, 2022). "TRIB3, a kind of pseudokinase, can inhibit synthesis of fatty acid by combining with E3 ubiquitin ligase and protect against diet-induced obesity by stimulating fatty acid oxidation in adipose of mice during fasting." (PMID 29152100, 2017). "The study investigates how the Trib3 gene influences energy balance and obesity." (PMID 39623091, 2024). "Recent studies showed that TRIB3 is a significant gene linking obesity and type 2 diabetes." (PMID 36105108, 2022). "Altogether, we could hypothesize that TRIB3 was of great importance during the adipogenesis, which would provide a new target for the treatment of obesity and obesity-related diseases." (PMID 35499169, 2022). "This suggests that targeting Trib3 could help treat obesity and related metabolic disorders." (PMID 39623091, 2024). "Obesity and type-2-diabetes in humans, as well as high-fat feeding in mice, have been shown to exhibit increased expression of Trib3 in skeletal muscle, while Trib3 knockout mice were protected from glucose-induced IR, suggesting TRIB3 to be a critical response factor in nutrient excess." (PMID 35418570, 2022). "The development of drugs that suppress the expression of Trib3 through the transcriptional regulation or activation of PKC, which specifically regulates COP1 activity, could be a potential strategy to prevent and treat diet- and aging-associated obesity and type 2 diabetes." (PMID 39623091, 2024).